CTSH (cathepsin H)
Diseases named in the same sentence as CTSH in open-access papers (continued):
Sharing a sentence is not in itself a finding about the gene and the disease.
cerebral small vessel disease (1 paper, 2023). Cerebral small vessel disease is the term currently used to pathological processes that affect the brain parenchymal circulation (arterioles, capillaries, and veins). "Future investigations could also query whether mutations in CD63 or CTSH are linked to human cerebral small vessel disease outside of CADASIL." (PMID 36753487, 2023).
colon cancer (1 paper, 2024). "Elevated levels of cathepsin H (CTSH) in colon cancer patients have been linked to MHC class II antigen presentation." (PMID 39736788, 2024).
diabetic kidney disease (1 paper, 2023). Progressive kidney disorder caused by vascular damage to the glomerular capillaries, in patients with diabetes mellitus. "Of note are the TYRO3 (tyrosine-protein kinase receptor), DLK1 (protein delta homologue 1) and CTSH (cathepsin H) proteins, which are significantly associated with diabetic kidney disease (DKD)." (PMID 36349687, 2023).
diabetic maculopathy (1 paper, 2025). Diabetic maculopathy (DM) is a type of diabetic retinopathy and it is a major eye complication and visual impairment amongst people with diabetes. "However, no statistically significant causal association was observed between Cathepsin H and DN, Cathepsin H and DR, or Cathepsin F and diabetic maculopathy, after adjusting for other types of cathepsins." (PMID 40616157, 2025). "Leveraging consortium-level genetic data (eQTLGen, GTEx) and functional validation (GSE94019, GSE102485), we identified Cathepsin H as a key pathogenic driver of PDR and diabetic maculopathy, with robust evidence from GSMR, MVMR, and cis-eQTL-based SMR." (PMID 40616157, 2025). "Our GSMR and IVW-MR analyses robustly identified Cathepsin H as a novel causal risk factor for DR and its severe subtypes PDR and diabetic maculopathy." (PMID 40616157, 2025). "Crucially, MVMR adjusting for protease family demonstrated substantial attenuation in Cathepsin H-DR association, while preserving robustness in PDR and diabetic maculopathy subgroups, indicating stage-dependent intensification of proteolytic effects." (PMID 40616157, 2025). "Crucially, MVMR accounting for protease family collinearity confirmed the independent causal role of Cathepsin H in PDR and diabetic maculopathy." (PMID 40616157, 2025). "Multivariable MR analysis further confirmed the independent causal role of Cathepsin H in PDR {inverse variance weighted (IVW): p = 0.003, OR = 1.054, 95% CI = 1.017–1.093} and diabetic maculopathy (IVW: p = 0.022, OR = 1.068, 95% CI = 1.009–1.130)." (PMID 40616157, 2025). "Complementary analyses, including cis-eQTL MR and SMR, further validated the causal roles of Cathepsin H in DR, PDR, and diabetic maculopathy." (PMID 40616157, 2025). "To validate the causal effect of Cathepsin H on DR, PDR, and diabetic maculopathy risks, we obtained cis-eQTL data from the eQTLGen Consortium." (PMID 40616157, 2025). "Initial GSMR analysis identified Cathepsin H as a risk factor for overall DR, PDR, and diabetic maculopathy, with findings strongly concordant with IVW-MR." (PMID 40616157, 2025). "We further used SMR analysis to validate the relationship among the cis-eQTL of Cathepsin H and DR, PDR, and diabetic maculopathy." (PMID 40616157, 2025). "By synergizing GSMR, MVMR, IVW-MR and SMR with multi-omics integration, this work not only establishes Cathepsin H as a novel therapeutic target for PDR and diabetic maculopathy but also pioneers a translational paradigm bridging genetic association to clinical intervention." (PMID 40616157, 2025). "Therefore, the IVW-MR further confirmed the GSMR results for Cathepsin H on DR, PDR and diabetic maculopathy, and cathepsin F on diabetic maculopathy." (PMID 40616157, 2025). "However, our results revealed that there were no causal relationships between Cathepsin H and immune phenotypes in DR pathogenesis, which suggested that immune cells did not act as a mediator in the pathway from Cathepsin H and DR, PDR, and diabetic maculopathy." (PMID 40616157, 2025).
emphysema (1 paper, 2014). "Interestingly, cathepsin H has been shown to be upregulated in an IL-13 induced emphysema murine model." (PMID 24729918, 2014).
glioblastoma (1 paper, 2014). The most malignant astrocytic tumor (WHO grade IV). "We noted an overlap of up-regulated genes with an immune signature reported in a glioblastoma profiling study, including MHC class I and II genes, the complement factors C1QA/B/C, FCGR3A, B2M, SOCS3, TLR2 and CTSH." (PMID 25593989, 2014).
hypoglycaemia (1 paper, 2025). "Following hypoglycemia, transient changes from baseline occurred in DKK1, cathepsin A, cathepsin G, cathepsin H, cathepsin S, cathepsin Z, parathyroid hormone (PTH), Sphingosine kinase 1 and 2 (SPK1/2), and interleukin-1 beta (IL1 beta) over the post-hypoglycaemia time course." (PMID 41373586, 2025).
infertile (1 paper, 2022). "The expression of LCP1, CTSH, BPIFB1 and Quiescin sulfhydryl oxidase 1 (QSOX1) is significantly higher in infertile receptive phase uterine lavage compared to fertile." (PMID 36589798, 2022).
inflammatory breast carcinoma (1 paper, 2014). An advanced, invasive breast adenocarcinoma characterized by the presence of distinct changes in the overlying skin. "Furthermore, CTSB and CTSH have been reported to be overexpressed in inflammatory breast cancer, as well as involved in cancer progression and invasion." (PMID 24932247, 2014).
lung diseases (1 paper, 2013). "Cathepsins play a role in ECM remodelling, with cathepsin D, H and K (CTSD, CTSH and CTSK) being associated with lung diseases." (PMID 23483898, 2013).
lung squamous cell carcinoma (1 paper, 2025). "Moreover, no risk association existed between CTSH and squamous cell lung carcinoma or small cell lung cancer." (PMID 41473685, 2025).
neuroblastoma (1 paper, 2026). Neuroblastoma (NB) is the most common solid, extracranial childhood tumor. "Six of these genes (CMBL, LY6E, KLRB1, CTSH, CD3D, and PTGDS) were utilized to construct a risk-scoring model that effectively stratified neuroblastoma patients into high- and low-risk groups with significantly distinct clinical outcomes (p < 0.001)." (PMID 41993132, 2026).
ovarian carcinoma (1 paper, 2021). A malignant neoplasm originating from the surface ovarian epithelium. "Eight immune factors (IFT57, MAL, ANXA4, SCRN1, LTBR, KIFAP3, HSPA5, and LTN1) were positively correlated with poor prognosis of ovarian cancer, whereas six immune factors (PSMB9, FOXJ1, CTSH, MIF, CTSD, and PSMB8) were negatively correlated with poor prognosis of ovarian cancer." (PMID 34109184, 2021).
primary biliary cirrhosis (1 paper, 2020). "On the other hand, cis-eQTLs for CTSH in LPS-stimulated myeloid cells and PHA-stimulated T cells both colocalised with primary biliary cirrhosis (PBC)." (PMID 32724101, 2020).
psoriasis (1 paper, 2019). An autoimmune condition characterized by red, well-delineated plaques with silvery scales that are usually on the extensor surfaces and scalp. "The psoriasis-associated supersets were also found to be closely linked in the blood network via KDs such as CTSH, IL1B, STAT1, and IFITM2." (PMID 30642337, 2019). "CTSH was surrounded by CTSS, CTSD and other critical factors involved in complement and adhesion (e.g., C3 and ICAM1) in the psoriasis network, suggesting that it might trigger inflammatory responses by regulating the neighbors in the network." (PMID 30642337, 2019).
skin inflammation (1 paper, 2023). "It was reported that mTORC2 and its downstream molecules, such as Akt and cathepsin H were essential for the barrier function of the skin, and the disruption of this axis was associated with AD, which led us to investigate the role of mTORC2 in the MC903-induced skin inflammation." (PMID 36983043, 2023).
small cell lung carcinoma (1 paper, 2025). Small cell lung cancer (SCLC) is a highly aggressive malignant neoplasm, accounting for 10-15% of lung cancer cases, characterized byrapid growth, and early metastasis. "Meta‐analysis of the two databases confirmed the absence of a causal relationship between CTSH levels and small cell lung cancer (OR = 1.06, 95% CI = 0.99–1.14, P = 0.09)." (PMID 41473685, 2025).
Usher syndrome (1 paper, 2025). A syndromic diseae characterized by the association of sensorineural deafness (usually congenital) with retinitis pigmentosa and progressive vision loss. "Several genes, such as IGHV1-69D, CTSH, and LMO7, exhibited significant upregulation in Usher syndrome, while others, including SLC3A2, ABLIM1, and CBS, were notably downregulated." (PMID 40723835, 2025).
tumor (23 papers, 2000 to 2025). "Research has shown that certain cysteine cathepsins mediated tumor progression, angiogenesis, and metastasis, but studies specifically focusing on CTSH in cancer have remained limited." (PMID 41473685, 2025). "Single‐cell transcriptome analysis also offered insights into the expression and function of CTSH in different cell types, elucidating its specific role within the tumor microenvironment." (PMID 41473685, 2025). "Specifically, CTSH was enriched in “mo‐Mac” in the tumor group, while it was enriched in “Alveolar Mac” in the normal group, suggesting potential functional differences of CTSH under varying disease states." (PMID 41473685, 2025). "Previous studies had shown that CTSH was abnormally expressed in various cancers (including breast, prostate, and colorectal cancers) and was involved in processes such as tumor invasion, metastasis, angiogenesis, and drug resistance." (PMID 41473685, 2025). "In the TCGA data, the samples with a low expression of CTSH exhibited worse survival in the tumor group, and CTSH displayed elevated expression in the normal group." (PMID 41473685, 2025). "Cathepsin H influences skin malignancy development by modulating signaling and activity within tumor cells." (PMID 39312365, 2024). "They include the hypoxia-inducible factor 1 subunit α, the CD44 stemness factor in the brain, cathepsin H (CTSH gene) which is a tumor invasive factor in HepG2, and extracellular matrix proteins." (PMID 39273194, 2024). "For the mRNA level, CTSH showed significantly higher expression in HCC than non-tumor samples (derived from GEPIA)." (PMID 36982347, 2023). "We also found that CAFs in the tumor stroma showed higher expression levels of cathepsin H compared with stromal cells in adjacent normal mucosa." (PMID 37085135, 2023). "Tumor cells can secrete cathepsin H to break down extracellular matrix, and at the same time reduce the synthesis of cadherin E to reduce the adhesion between cells, so as to facilitate tumor metastasis." (PMID 33510294, 2021). "In a model of pancreatic islet carcinogenesis, deletion of cathepsin H significantly altered angiogenic switching of pre-malignant hyperplastic islets and ultimately a reduction in the number of tumours formed." (PMID 29666124, 2018). "Cathepsin H is a cysteine protease considered to play a major role in tumor progression, however, its precise function in tumorigenesis is unclear." (PMID 22933963, 2011). "Changes in cathepsin H expression were also detected by immunohistochemistry as elevated cathepsin H staining in tumour epithelial cells." (PMID 10755408, 2000). "However, protein level analysis from the HPA revealed significantly higher CTSH protein expression in the tumor group, consistent with plasma protein‐level CTSH expression in the MR analysis." (PMID 41473685, 2025). "However, analysis of CTSH protein expression levels in the HPA database demonstrated markedly higher expression in the tumor group relative to the normal group." (PMID 41473685, 2025). "Among them, human malignancies were selected because of their high CTSH tumor expression." (PMID 36982347, 2023). "Finally, we observed that cathepsin H expression was present not only in superficial T1CAFs (ie, where the biopsy specimens were taken), but also in T1CAFs located in deeper tumor areas and at the invasive front." (PMID 37085135, 2023). "Cathepsin H, which is one of the enzymes involved in the lysosomal proteolytic pathway, showed significantly increased activity in the W group, but this increase was less pronounced in the LW group (P < 0.047); in this case, the diet modulated the effect of tumour growth." (PMID 24383706, 2014). "In this study, tumor-bearing models and HCC cell lines were used to observe the effect of CTSH on radioresistance." (PMID 36982347, 2023). "Finally, we validated its role in inhibiting tumor proliferation and metastasis in LUAD cells by knockdown of CTSH." (PMID 39839650, 2024).
tumor (continued). "Strikingly, qPCR analysis revealed that CTSH was only differentially expressed in T1CAFs, but not in tumor fibroblasts from earlier or later CRC stages." (PMID 37085135, 2023). "Intriguingly, consistent up-regulation of cathepsin H was observed only in T1CAFs and not in tumor fibroblasts from any other CRC stage, indicative of a T1-specific mechanism of matrix remodeling." (PMID 37085135, 2023). "For instance, the high expression of CTSH in PTC (up-regulated by 6.78x with respect to NOR) was related to the tumor progression and migration of cancer cells." (PMID 32887258, 2020).
cancer (20 papers, 2000 to 2025). A tumor composed of atypical neoplastic, often pleomorphic cells that invade other tissues. "Cathepsin H has been reported to be associated with cancer and other major diseases." (PMID 38590662, 2024). "Although radioresistance is reported with high glycolysis, the underlying mechanism between radioresistance and cancer metabolism, as well as the role of cathepsin H (CTSH) within it, remain unclear." (PMID 36982347, 2023). "In this study, we elucidated a comprehensive CTSH-involved cancer metabolism that inhibits apoptosis in driving radioresistance." (PMID 36982347, 2023). "In summary, our study found that the cancer metabolic switch and apoptosis were regulated by CTSH signaling, leading to the occurrence of radioresistance in HCC cells and suggesting the potential value of HCC diagnosis and therapy." (PMID 36982347, 2023). "In this context, relatively radioresistant HCC cells were highly addicted to glycolytic metabolism, but when CTSH was knocked down, this cancer metabolic switch was significantly reversed." (PMID 36982347, 2023). "Despite being implicated in cancer development and the processing of neurotransmitters, the role of CTSH, a ubiquitously expressed lysosomal cysteine protease in cancer apoptotic process, is rarely reported." (PMID 36982347, 2023). "Already in the earliest stage of CRC, cancer cell invasion is promoted by CAFs via direct interactions with epithelial cancer cells and stage-specific, cathepsin H–dependent ECM remodeling." (PMID 37085135, 2023). "We also proposed that OAS1 expression enhancement can induce the anti-cancer effects of interferon-gamma, while suppression of CTSH hinders formation of focal adhesions." (PMID 34249670, 2021). "Although cathepsin H activities were most commonly elevated in Dukes' C cancers at all colon sites, both specific activity and C/N ratios were significantly higher for cancers of the left colon compared to other colon locations." (PMID 10755408, 2000). "A subset of 43 paired extracts analysed on Western blots also revealed consistent changes in cathepsin H protein forms in cancers." (PMID 10755408, 2000). "Currently, CTSH has already been found to be involved in Talin processing for focal adhesion of migrating PC‐3 cells, suggesting that intracellular protein hydrolysis played a role in regulating cancer cell migration." (PMID 41473685, 2025). "Therefore, our discovery can explain the paradox that CTSH is highly expressed and associated with poor prognosis in certain types of human cancer, such as HCC, but has relatively low expression in other cancers." (PMID 36982347, 2023). "To solve the elusive questions above, here, we outline a comprehensive CTSH-involved metabolic mechanism to regulate apoptosis and radioresistance, suggesting novel therapeutic strategies in radiation sensitization via disrupting cancer metabolism." (PMID 36982347, 2023). "The high CTSH expression cancers are likely to be highly malignant." (PMID 36982347, 2023). "As mitochondria are known to play an important role in metabolism and apoptosis and the cancer metabolic switch is important for cancer cell fate, we wondered whether CTSH was affecting cell fate by regulating the metabolic switch." (PMID 36982347, 2023). "In addition, this mechanism likely acted as a common feature among patients with higher CTSH levels in other cancers." (PMID 36982347, 2023). "The role of cathepsins, including CTSH, in cancer progression is somewhat contradictory." (PMID 37064098, 2023). "Consistent with these laboratorial results, our clinical bioinformatic analysis also revealed that the CTSH-mediated cancer metabolic switch (Warburg effect) likely contributed to tumorigenesis and was correlated to poor prognosis in clinical HCC cohorts on both a transcriptome and a proteome level." (PMID 36982347, 2023). "Remarkably, CTSH was related with poor prognosis in all these cancers." (PMID 36982347, 2023).
cancer (continued). "Additionally, CTSH correlated negatively with Ki67, a proliferation marker for cancer cells." (PMID 37507593, 2023). "However, whether CTSH is involved in the cell death of cancer still remained unclear." (PMID 36982347, 2023). "In this context, CTSH appears to be important to maintain cancer metabolism in cells with higher glycolytic activity but it is not so important for cancer cells that have less glycolytic activity." (PMID 36982347, 2023).
adenocarcinoma (4 papers, 2023 to 2025). A common cancer characterized by the presence of malignant glandular cells. "CTSH is highly expressed in small cells and in adenocarcinomas." (PMID 38883596, 2024).
neurodegenerative disease (3 papers, 2024 to 2025). A disorder of the central nervous system characterized by gradual and progressive loss of neural tissue and neurologic function. "PD is a neurodegenerative disease, and lysosomal dysfunction, attributed to the accumulation and spread of neurotoxic protein oligomers, including alpha-synuclein, is common in most neurodegenerative diseases, with CTSH playing a significant role." (PMID 38872630, 2024).
neurological disease (2 papers, 2021 to 2025). "A recent in vivo study showed a prominent upregulation of cathepsin H expression in brain microglia after LPS injection, supported by an in vitro study confirming a potential role of cathepsin H in the neuroinflammatory pathogenesis of neurological diseases." (PMID 34944440, 2021). "Also, 59 unique proteins were associated with AD, and 10 of them (17%) showed an association with AD and an additional neurological disease (CTF1, NSF and PRSS53 with PD; SIGLEC9 with ALS; CR1, CTSH, PARP1 and PVR with MS; LRRC37A2 with both PD and ALS; and IDUA with PD, ALS and MS)." (PMID 40037332, 2025). "Ten proteins showed co-localization with a neurological disease using both plasma protein abundance and plasma mRNA abundance (SIRPA, CTSH and CD33 with AD; and ASF1A, FCRL3, VEGFB, TYMP, PVALB, LMAN2 and CD5 with MS)." (PMID 40037332, 2025).
digestive system tumors (1 paper, 2024). "This analysis encompassed a total of nine cathepsins include cathepsin B, cathepsin E, cathepsin F, cathepsin G, cathepsin H, cathepsin L2, cathepsin O, cathepsin S, and cathepsin Z, and six digestive system tumors (HCC, PCa, BTC, CRC, GC, and EC)." (PMID 38590662, 2024).
immune disease (1 paper, 2025). "The analysis revealed the significant enrichment of genes such as HLA-DQB1, HLA-DPA1, S100A8, SFRP1, CD247, CTSH, and LAMP3, which are linked to inflammatory and immune disease pathways." (PMID 40426861, 2025).
kidney disease (1 paper, 2023). "Whereas CTSH and DLK1 have not been associated with kidney disease, studies have shown increased TYRO3 mRNA expression and increased circulating and urinary TYRO3 levels in patients with DKD, further supporting a causal role." (PMID 36349687, 2023).